MHENCR (melanoma highly expressed competing endogenous lncRNA for miR-425 and miR-489)
Gene: Long non-coding RNA gene on chromosome 20 (63,626,148 to 63,628,825, forward strand). Ensembl gene ENSG00000232442.
Diseases named in the same sentence as MHENCR in open-access papers:
MHENCR is named in the same sentence as 4 diseases in open-access papers, as found by Europe PMC text mining. Sharing a sentence is not in itself a finding about the gene and the disease. The quoted sentences say what the papers report.
melanoma (3 papers, 2020 to 2025). A malignant, usually aggressive tumor composed of atypical, neoplastic melanocytes. "Other than that, ROR1, FOXC1, MIF, TGFβ, lncRNA SNHG17, MIAT, MHENCR, OR3A4 and H19 regulate proliferation, progression, migration, invasion, metastasis or EMT-like transition though PI3K/AKT pathway in melanoma cells." (PMID 32333246, 2020). "Remarkably, CTD-3184A7.4, also termed as MHENCR, and RP11-108L7.15 have been reported to promote melanoma progression via PI3K-Akt signaling, and cell proliferation, migration and invasion in glioblastoma, further suggesting that these lncRNAs might play functional roles in COAD progression." (PMID 34603397, 2021).
tumor (1 paper, 2025). "MHENCR acts as a tumor suppressor, upregulated by treatment, potentially enhancing alkaliptosis sensitivity." (PMID 40264452, 2025).
MHENCR also shares sentences with these, for which no sentence is quoted: cancer (1 paper); glioblastoma (1).